NLRP3 (NLR family pyrin domain containing 3)
Diseases named in the same sentence as NLRP3 in open-access papers (continued):
Sharing a sentence is not in itself a finding about the gene and the disease.
infection (continued). "This argues that abolishment of NLRP3 inflammasome signaling during IAV infection is harmful and that early NLRP3 inflammasome activation is necessary for controlling the infection and viral clearance." (PMID 28740490, 2017). "Using mice-expressing human POP2, this study confirms the anticipated in vivo functions of POP2, that NF-κB and Nlrp3 inflammasome-dependent cytokine responses to inflammatory challenge and infection are tempered by POP2." (PMID 28580947, 2017). "To determine the involvement of the upstream and the downstream signals of IL-1β, we assessed the expression levels of the upstream NLRP3 inflammasome in dendritic cells and different glial cells from resistant B6 and susceptible SJL mice after TMEV infection." (PMID 28445497, 2017). "The effects of HGPg infection on the mRNA expression of NLRP3 in HGFs were studied using infected cells with P. gingivalis grown on NG or under HG conditions." (PMID 28083517, 2016). "The total number of lung cells recovered and the frequencies of T and NK cells were similar between wildtype, Casp1/11-/-, and Nlrp3-/- mice over the course of infection." (PMID 27926940, 2016). "This study proposes a new, genetic basis of susceptibility, exemplified by the disease phenotype in Asc-/- or Nlrp3-/- mice or resistance in Il1b-/- mice that were protected from infection." (PMID 27732661, 2016). "Infections at various MOIs showed that M. bovis-induced upregulation of both NLRP3 and AIM2 was dose-dependent." (PMID 27043315, 2016). "Mice with genetic deletion of Nlrp3 have diminished inflammation in Hla-induced pneumonitis models and decreased severity of infection in a mouse model of Staphylococcal pneumonia." (PMID 27043625, 2016). "As infection progressed, the quantity of NLRP3 mRNA progressively decreased at 12 h p.i. compared to 4 h p.i.." (PMID 27362650, 2016). "In turn, EV-A71 infection inhibits NLRP3 inflammasome activation by directly cleaving NLRP3 with 2A and 3C proteinases." (PMID 26784219, 2016). "Immature monocytic cells (mMDSC) declined late during Ft LVS infection of Nlrp3-/- mice, but at the same time point, mature F4/80+ macrophages were also decreased." (PMID 27926940, 2016). "Likely through promoting necrotic/necroptotic cell death, Nlrp3 contributes to the immature myeloid response and necrotic pathology that characterize lethal infection with Francisella tularensis." (PMID 27926940, 2016). "We next examined the effect of delaying NLRP3 inflammasome inhibition to the later stages of HKx31 infection." (PMID 27283237, 2016). "These metabolic defects appeared on a similar timescale as initiation of NLRP3 inflammasome formation, suggesting that infection with S. typhimurium has a direct effect on glycolytic flux in host cells." (PMID 27011353, 2016). "Infection of the cells with CY-17 caused a further decrease in ASC and NLRP-3 staining (quantified in S8B Fig)." (PMID 27732661, 2016). "Here we proposed that YopM regulated necrotic cell death through NLRP3 in the later time during their infection." (PMID 27929533, 2016). "Card9−/− macrophages secreted 2.5 times more IL-1β than WT BMDMs at both 6 and 24 h post infection, time points known to involve NLRP3 activity in response to Salmonella infection." (PMID 27670879, 2016). "Remarkably, while all wildtype mice succumbed to infection with the highly virulent and clinically relevant Type A strain SchuS4 (10 cfu) by 6–7 days, a small, but significant proportion (20%) of Nlrp3-/- mice survived." (PMID 27926940, 2016). "IL-1β induction in response to C. albicans was shown previously to depend on the NLRP3 inflammasome in different infection models and NLRP3 was required in the hematopoietic compartment." (PMID 27632536, 2016). "NLRP3 protein exhibited an apparent change at 6 and 24 h after B. melitensis 16M infection, while the AIM2 protein underwent a marked change at 6 h." (PMID 27907115, 2016).
infection (continued). "Nlrp3–/– mice showed increased resistance to either infection, as revealed by the reduced fungal or bacterial load, IL-1β production and lung inflammatory cell recruitment." (PMID 26972847, 2016). "In contrast, ASC staining was reduced after infection with the virulent strains (P < 0.001) and NLRP-3 showed a weaker staining (P < 0.01)." (PMID 27732661, 2016). "Although others have shown that the NLRP3 inflammasome controls severity of infection, future studies will have to address if lack of key components of this inflammasome also leads to reduced iBALT formation." (PMID 27579026, 2016). "On the other hand, in monocytes, activation of TLR7 by HCV virions was associated to activation of the inflammasome pathway, promoting the secretion of IL-1β and IL-18 in a NLRP3-dependent and infection independent pathway." (PMID 27610098, 2016). "We confirmed that infection with either wildtype S. typhimurium or S. typhimurium lacking the SPI-1 secretion system (which genetically limits S. typhimurium to activate NLRP3) induced inflammasome formation." (PMID 27011353, 2016). "Although NLRP3 is activated by many pathogens, it only appears to be critical for host defense for a limited number of specific infections." (PMID 27551512, 2016). "As early as 4 h p.i., infection with R. australis at an MOI of 6 significantly increased NLRP3 transcripts in WT macrophages." (PMID 27362650, 2016). "After B. melitensis 16M infection in differently treated cells, Western blot was used to detect the expression of NLRP3 protein levels at all of the time points." (PMID 27907115, 2016). "NLRP3 activity was instead defective in Il1r1–/– mice, in which the attenuated IL-1β production was concomitant with a reduced disease severity during infections." (PMID 26972847, 2016). "NLRP3 inflammasome-dependent pyroptosis is a dominant mechanism of C. albicans-induced macrophage death early in infection." (PMID 27303738, 2016). "Next we compared WT and NLRP3-deficient animals, and found an increased S. pneumoniae-induced barrier dysfunction in Nlrp3−/− compared to WT animals at 24 h post infection." (PMID 27476670, 2016). "As Nlrp3 appears dispensable for resistance to infection with Francisella novicida, we considered its role during infection with the virulent Type A strain SchuS4 and the attenuated Type B live vaccine strain LVS." (PMID 27926940, 2016). "This suggests that while NLRP3 activity is critical in controlling systemic dissemination of the infection, NLRC4 activity in stromal cells is required for the protection from mucosal candidiasis." (PMID 27994587, 2016). "NLRP3-dependent but caspase-1-independent necrosis has been reported to occur in response to infection with Mtb and Shigella flexneri." (PMID 27191591, 2016). "HGPg infection also induced an increase in NLRP3 and mature 68 kD SREBP-1c protein expression in HGFs in a time-dependent manner." (PMID 28083517, 2016). "Approximately 15% of Nlrp3-/- mice survived infection with a four-fold higher challenge dose, but all succumbed with a 20-fold higher challenge dose." (PMID 27926940, 2016). "Infection with IAV leads to activation of the Nlrp3 inflammasome in a process requiring the type I IFN-induced RNAse L/OAS system, while the virus actively suppresses IL-1β production and Nlrp3 activation via the NS1 protein." (PMID 27579026, 2016). "As with LVS and SchuS4 infection, the lungs of Nlrp3-/- mice displayed reduced bacterial burdens at 3 and 5 days post-Fn infection." (PMID 27926940, 2016). "The NLRP3 inflammasome complex can be activated by both exogenous (including infection, tissue damage, and metabolic dysregulation) and endogenous molecules such as extracellular ATP, hyaluronan, Aβ fibrils, and uric acid crystals." (PMID 27652274, 2016).
infection (continued). "The appearance of neutrophils in the lung on day 1 precedes reduced bacterial burden over the course of infection in Nlrp3-/- mice, suggesting that Nlrp3 promotes host lethality in wildtype mice by restricting the appearance of these cells." (PMID 27926940, 2016). "At 6 h after B. melitensis 16M infection, NLRP3 and AIM2 in the O-A and OA-IA cells were significantly higher than in the control cells (P < 0.01), indicating that at 6 h B. melitensis 16M infection activated NLRP3 and the AIM2 inflammasome." (PMID 27907115, 2016). "Ft infected Nlrp3-/- mice depleted of Gr-1+ cells succumb to infection, indicating that the neutrophils observed at 1 dpi are critical for protection." (PMID 27926940, 2016). "NLRP3 is mainly responsible for the detection of infection-derived molecules such as lipopolysaccharide." (PMID 26881256, 2016). "ASC was shown to pull down NLRP-3 in nuclear extracts of uninfected cells but after infection, a reduction in ASC/NLRP-3 interaction was detected suggesting that a loss of ASC/NLRP-3 interaction in the nuclear compartment accompanies MMP7 activation." (PMID 27732661, 2016). "Contrary to the protective function of the NLRP3 upon infection with the respiratory pathogen Chlamydia pneumoniae, caspase-1 activation promotes the growth of C. trachomatis in cervical epithelial cells." (PMID 27994587, 2016). "The results of this study demonstrate that HGPg infection not only induces NLRP3 upregulation, but also enhances active caspase-1 and mature IL-1β expression in HGFs." (PMID 28083517, 2016). "Similar to LVS infection, lung bacterial burdens were significantly reduced in Nlrp3-/- mice at 5 days post-SchuS4 infection." (PMID 27926940, 2016). "Exacerbated inflammasome activation was dependent on NLRP3, and all host killing by the mmm1 mutant at later time points in infection was by pyroptosis." (PMID 27303738, 2016). "Because TOE-A5/nleA infection inhibited the assembly of the NLRP3 inflammasome, we examined the degree of de-ubiquitination of NLRP3." (PMID 26332984, 2015). "Infection of the mouse A/E pathogen C. rodentium has been shown to activate the NLRP3 inflammasome, which is critical for the production of IL-1β and IL-18 and protection in mouse macrophages." (PMID 26332984, 2015). "In fact, even for intranasal infection with a low virulence acapsular strain of C. neoformans, NLRP3 was required for effective lung leukocyte infiltration and fungal clearance." (PMID 26204108, 2015). "Meanwhile, NLRP3-/- mice and Caspase-1-/- mice appeared to produce much less viruses at 72h of infection as compared to the WT controls." (PMID 26367131, 2015). "RIPK1 function was shown do be essential for activation of the NLRP3 inflammasome upon infection with RNA viruses, such as Sendai virus or Influenza A." (PMID 26297639, 2015). "Our studies support this notion, and showed that BMDM deficient in RIP3, NLRP3, ASC, and MyD88 all had pathogen specific reductions in cytotoxicity following infection." (PMID 26659062, 2015). "We first checked expression of NLRP3 in the tissue and found up-regulation of NLRP3 upon S. pneumoniae D39 and D39Δply infection." (PMID 26317436, 2015). "Following challenge with P. gingivalis at a multiplicity of infection (MOI) of 100, expression of the genes encoding NLRP3 and NLRP1 was increased, but with the gene encoding ASC being discordant and the gene encoding pro-IL-18 was downregulated." (PMID 25866631, 2014). "They demonstrated that both NLRC4 and NLRP3 knockout macrophages can cleave caspase-1 as wild-type macrophages eight hours after infection." (PMID 24626296, 2014). "A recent study also showed that the current acellular vaccine acts through promoting a NLRP3-independent IL-1 response that generates robust Th1 and Th17 responses, a phenomenon also observed during primary infection." (PMID 25198773, 2014).
infection (continued). "The expression level of NLRP3 in VK627 infection group at 3 dpi and in rVK627E group at 5 dpi and 6 dpi were significantly higher than the control (P < 0.05)." (PMID 25547136, 2014). "The NLRP3 inflammasome is a molecular platform that is activated upon cellular infection or stress and triggers the maturation (activation) and secretion of IL-1β, to engage the inflammatory response." (PMID 25216263, 2014). "WNV activates the NLRP3 inflammasome to produce mature IL-1ß, which helps control infection in the brain through a pathway that synergizes with type I IFN signaling." (PMID 24743949, 2014). "Confirming what we observed during infection with B. pseudomallei, production of IL-1β following infection with B. thailandensis was dependent on NLRP3, ASC, and caspase-1 while pyropotosis was dependent on NLRC4." (PMID 25166912, 2014). "As the lung and brain showed significant differences in these two H9N2 avian influenza virus strains infection, we chosen to detect the expression patterns of NLRP3 and its related cytokines of IL-1β and TNF-α." (PMID 25547136, 2014). "We measured concentrations of TNF-α, IFN-γ, MCP-1, IL-6, IL-10 and IL-12p70 in plasma of Asc−/−, Nlrp3−/− and WT mice 2 and 5 days after infection." (PMID 25115174, 2014). "To specifically determine if NLRP3 inflammasome activation by ASC/caspase-1 is the primary source of protective IL-1β in the context of Tc infection, we conducted further studies in primary bone marrow-derived mφs from NLRP3-/- mice and matched controls." (PMID 25372293, 2014). "The immunohistological results showed that the positive cells of NLRP3, IL-1β and TNF-α altered the positive levels of original cells in tissues and infiltrated inflammatory cells which caused by H9N2 infection." (PMID 25547136, 2014). "Both VK627 and rVK627E infection can active the expression of NLRP3, IL-1β and TNF-α in the lung and brain of BALB/c mice at different levels and this also improved that site 627 in PB2 takes part in the virulence of H9N2." (PMID 25547136, 2014). "In rVK627E infection group, the expression level of NLRP3 continuously increased till achieving its highest level at 5 dpi." (PMID 25547136, 2014). "Because the IL-1R signaling pathway is required for clearance of B. pertussis and rapid vaccine-mediated immunity, it was suggested that NLRP3-inflammasome activation of IL-1β would be required for controlling infection." (PMID 25198773, 2014). "Previous work has suggested that infection with B. pertussis leads to activation of the NLRP3/caspase-1 inflammasome and this activation depends on the pore-forming activity of the adenylate cyclase toxin." (PMID 25198773, 2014). "The expression level of NLRP3 in VK627 infection group was higher than rVK627E group and the control at 1 dpi and then achieved its peak at 3 dpi before declined at 5 and 6 dpi." (PMID 25547136, 2014). "In the absence of priming, minimal levels of IL-1β were secreted by WT, Nlrp3−/− and Nlrc4−/− macrophages during infection with WT and Δhly L. monocytogenes." (PMID 24058709, 2013). "Here, we demonstrate that infection with V. parahaemolyticus triggers both NLRP3- and NLRC4-inflammasome activation." (PMID 23357873, 2013). "Cathepsin B appears to be required for NLRP3 activation in response to infection with T. cruzi, as pharmacological inhibition of cathepsin B abrogates IL-1β secretion." (PMID 24098823, 2013). "While NLRP3 is involved in many inflammatory disorders, little is known about the role of NLRP3 in controlling infections." (PMID 24098823, 2013). "In conclusion, we have demonstrated a protective role for ATP in fighting infection, and this role is related to NLRP3 inflammasome activation." (PMID 23717478, 2013). "The protein tyrosine kinase Syk has been implicated in Mtb-mediated inflammasome activation, which is consistent with its previously identified role in activating the NLRP3-inflammasome after infection with the fungal pathogen Candida albicans." (PMID 24130966, 2013).
infection (continued). "Another recent report revealed that activation of Rac1 in response to infection is important to NLRP3/ASC-dependent caspase-1 activation in response to Chlamydia pneumoniae by human mononuclear cells." (PMID 24324933, 2013). "In summary, the infection of murine dendritic cells with the primary fungal pathogen P. brasiliensis primes, via Syk signaling, and activates the caspase-1-dependent NLRP3 inflammasome." (PMID 24340123, 2013). "Altogether, our results demonstrate that the NLRP3 inflammasome senses and responds to P. brasiliensis yeast cells infection and plays an important role in host defense against this fungus." (PMID 24340123, 2013). "In epithelial cells, which are the primary sites of infection by C. trachomatis, as well as in human monocytes and dendritic cells, NLRP3 and ASC mediate inflammasome-dependent activation of caspase-1 and secretion of cytokines in response to C. trachomatis." (PMID 24324933, 2013). "Such insights are required to define the roles of NLRP3 and IL-1β in host response to infection, and to establish a potential therapeutic application to this knowledge." (PMID 24312491, 2013). "Infection with the ΔtdhASΔh1 mutant confirmed that NLRP3/NLRC4-inflammasomes activation is triggered by T3SS1." (PMID 23357873, 2013). "The NLRP3 inflammasome is the most characterized inflammasome activated by cellular infection or stress, which is responsible for the maturation of proinflammatory cytokines IL-1β and IL-18." (PMID 23942110, 2013). "This study was performed to better characterize the role of NLRP3 in early stages of infection and to determine if administration of IL-1β to Nlrp3−/− mice would bypass the lack of NLRP3 inflammasome." (PMID 24312491, 2013). "This is in line with recent studies showing that infection of cells with C. trachomatis and C. pneumoniae led to activation of caspase-1 depending on NLRP3 and ASC inflammasome." (PMID 22276187, 2012). "We first focused on the NLRP3 since this NLR protein is an important component of inflammasome complex during infections with various pathogens, including respiratory viruses like influenza A virus." (PMID 22295065, 2012). "In this study, we systemically examined the role of IL-1 signaling in WNV infection to show that IL-1β signaling driven by the NLRP3 inflammasome acts to mediate protective immunity against infection." (PMID 23209411, 2012). "IL-1β release during infection requires NLRP3/ASC inflammasome complex that activates caspase-1, the enzyme required for processing pro-IL-1β into mature IL-1β." (PMID 22295065, 2012). "The induction of TUNEL positive cells by Mtb was similar, about 40%, in BMDCs of all the different mouse strains, except for the Nlrp3−/− cells in which the level of TUNEL positive cells increased to about 50% after 24h of infection." (PMID 22911706, 2012). "NLRP3 inflammasome serve as the platform for caspase-1 activation (and IL-1β release) during infection with both DNA (adenovirus, herpes virus, vaccinia virus) and RNA (influenza A virus, mouse Sendai virus, mouse encephalomyocarditis virus) viruses." (PMID 22295065, 2012). "Our results showed that upon infection wildtype BMMs produced IL-1β whereas IL-1β production in the Nlrp3 knockout macrophages was completely abolished." (PMID 22276187, 2012). "Our results thus link phagosomal damage and Syk activity to NLRP3-mediated necrotic death triggered by M. tuberculosis ESAT-6 during infection." (PMID 21740493, 2011). "Infection of macrophages with Listeria monocytogenes induces the activation of caspase-1 via NLRP3, NLRC4 and AIM2 inflammasomes." (PMID 22019906, 2011). "We next assessed the role of NLRC4 and NLRP3 in protection from systemic dissemination of infection." (PMID 22174673, 2011). "Taken together, our data implicated phagosomal damage and Syk activity as two host factors that contributed to the NLRP3-mediated necrotic death triggered by M. tuberculosis ESAT-6 during infection." (PMID 21740493, 2011).